LDHA (lactate dehydrogenase A)
Diseases named in the same sentence as LDHA in open-access papers (continued):
Sharing a sentence is not in itself a finding about the gene and the disease.
infection (27 papers, 2015 to 2026). The state of being infected such as from the introduction of a foreign agent such as serum, vaccine, antigenic substance or organism. "The results showed that, compared with the control group, there were distinct dark brown labeled LDHA proteins in the kidney and lung on day 7 after infection with CSFV." (PMID 40265937, 2025). "Liu reported that LDHA translocated into the nucleus in response to increased ROS driven by HPV16/18 infection in cervical epithelial cells." (PMID 37298317, 2023). "While EPO was downregulated, GLUT1 and LDHA expression was significantly induced upon infection especially at 24 h post infection." (PMID 36611805, 2022). "Interestingly, the L-lactate content of cells infected with CSFV after knockdown of LDHA was significantly reduced compared to the CSFV-infected group after transfection with siNC, suggesting that CSFV infection is dependent on LDHA to induce L-lactate production." (PMID 40265937, 2025). "Furthermore, the impact of LDHA inhibition on immune responses to infection remains poorly studied." (PMID 32034005, 2020). "In addition, other important checkpoints in glycolysis, namely phosphofructokinase (gene PFKP up-regulated in primary and cytokine activated NK cells at 6 h post-infection) and lactatedehydrogenase (gene LDHA, up-regulated in primary and primed NKC at 3 h and 6 h) were up-regulated." (PMID 27242763, 2016). "The elevation of HIF-1α expression was consistent with the upregulation of HIF-1α target genes, including GLUT1 and LDHA, observed in PEDV-infected cells, supporting the involvement of HIF-1α in glycolytic activation during infection." (PMID 41512444, 2026). "By contrast, Mtb CDC1551 infection significantly upregulated the expression of selective markers of glycolysis (ADPGK and LDHA) and all tested TCA cycle and gluconeogenesis genes, compared to the uninfected controls." (PMID 38980014, 2024). "Seven infection/inflammation-related proteins in our assay, S100A9, VIM, LGALS1, APCS, MMP9, LDHA, and CRP, were elevated in TB-PEs and the other-infectious-PEs." (PMID 35197508, 2022). "The infection with wild-type and ΔdotA C. burnetii increases the expression of PKM2 and LDHA in normoxic and hypoxic BMDM, and the expression of Glut1 and PDK1 only in normoxic BMDM." (PMID 35755850, 2022). "The LDHA isoform of lactate dehydrogenase catalyzes the conversion of pyruvate to lactate, and following LVS infection, LDHA expression increased ~6-fold by 6 hpi." (PMID 35693822, 2022). "Furthermore, gene expression of glycolytic enzymes, lactate, and glutamine metabolism (G6PDH, PKLR, PFKL, LDHA, LDHB, GLS1, GLS2, and GLUL), were upregulated in primary mouse (hACE2) and human hepatocytes upon infection compared to controls." (PMID 35978143, 2022). "Infection also induces dramatic changes to bioenergetics in intestinal epithelial cells, with transition from oxidative phosphorylation (OXPHOS) to aerobic glycolysis and higher abundance of SGLT4, LDHA, and MCT4." (PMID 31610608, 2020). "Infection with HIF-1α shRNA lentivirus (HIF-1α-shRNA-1 and HIF-1α-shRNA-2) specifically prevented HIF-1α expression, but not HIF-2α expression, in RCC4 cells, which was further confirmed by detecting LDHA protein (a specific downstream target of HIF-1α)." (PMID 30125331, 2018). "Notably, the copy number of CSFV increased slowly at 12–24 h after infection, and the fastest at 24–48 h, which may be one of the reasons why LDHA mRNA levels did not increase at 24 h after CSFV infection but increased significantly at 48 h." (PMID 40265937, 2025). "Notably, HIF-1α is important for neutrophil survival in normoxia as well as hypoxia, and VEGFA and many other HIF-1α target genes, but not HIF1A itself, are upregulated following LVS infection including HK2, LDHA, PDK1 and SCL2A1." (PMID 35873156, 2022).
adenocarcinoma (8 papers, 2015 to 2026). A common cancer characterized by the presence of malignant glandular cells. "Subsequent H&E staining identified adenocarcinoma in the liver section of the LDHA‐OE group, while no liver metastasis lesion was identified with the control group." (PMID 34185423, 2021).
metabolic disorders (5 papers, 2023 to 2025). "ccRCC, characterized by high glucose uptake and enhanced levels/activities of glycolytic enzymes, such as hexokinase and LDHA, has been aptly labeled as a metabolic disease." (PMID 37547725, 2023). "DXT-M achieved this by modulating a network of metabolites (including citrate, taurine, glutamate, alanine, and others), which interact with targets of hepatic drug-metabolising enzymes, NOS3, and LDHA, thereby correcting endogenous metabolic disorders through intrinsic target molecules." (PMID 41155650, 2025).
cardiovascular disease (3 papers, 2024 to 2025). "LDHA is closely associated with the occurrence of cardiovascular diseases." (PMID 40800583, 2025).
myopathy (3 papers, 2015 to 2022). A disease of the muscle in which the muscle fibers do not function properly. "Among these proteins, some are associated with a primarily neuromuscular disorder (TELT, HSPB8, HXK1, PRPS1) or myopathy (LDHA)." (PMID 34360601, 2021).
neuromuscular disease (3 papers, 2015 to 2021). "The βF1-ATPase/LDHA ratio, which has been recently described as a potential biomarker of neuromuscular diseases, failed in the discrimination of IMs except for sIBM patients, which showed an increase of the ratio." (PMID 28183315, 2017).
bacterial infection (2 papers, 2017 to 2022). "For LDHA, a minor increase was observed after 8 h of bacterial infection in cells expressing HIF-1α." (PMID 28401064, 2017). "In summary, pathogenic bacterial infection upregulated PKM, LDHB, LDHA, ALDOA, PGD, GPI, and ALDOC, increased ATP production, which promotes leukocyte recruitment and NALP3-inflammasome activation, increases NADPH production, and promotes ROIs modulating inflammation and injury." (PMID 36335251, 2022).
inflammation (2 papers, 2021 to 2023). Aberrant reaction of the microcirculation characterized by movement of fluid and leukocytes from the blood into extravascular tissues. "LDHA was identified as a potential marker in allergic alveolitis, airway inflammation, allergic encephalomyelitis, asthma disease." (PMID 34394070, 2021).
LDHA also shares sentences with these, for which no sentence is quoted: prostate adenocarcinoma (5 papers); colorectal adenocarcinoma (4); gallbladder carcinoma (4); mesothelioma (4); multiple myeloma (4); pulmonary hypertension (4); fibrosis (3); malignant glioma (3); rheumatoid arthritis (3); uterine sarcoma (3); acute kidney injury (2); benign tumors (2); digestive tumors (2); fumarate hydratase deficiency (2); Glucose intolerance (2); hyperinsulinism (2); Hypertension (2); idiopathic pulmonary fibrosis (2); malignant mesothelioma (2); malignant pleural mesothelioma (2); McArdle disease (2); non-Hodgkin lymphoma (2); rectal adenocarcinoma (2); rectal cancer (2); thyroid tumor (2); acute lymphoblastic leukemia (1); adrenal cancer (1); adrenocortical carcinoma (1); allergic rhinitis (1); amyotrophic lateral sclerosis (1).
A further 83 diseases each share a sentence with LDHA in 1 paper.